RN7SL377P (RNA, 7SL, cytoplasmic 377, pseudogene)
Gene: Miscellaneous RNA gene on chromosome 7 (72,822,894 to 72,823,171, reverse strand). Ensembl gene ENSG00000266569.
Homologues: Paralogues in human: Metazoa_SRP (79% identical), RN7SL48P (77% identical), RN7SL32P (76% identical), RN7SL279P (76% identical), Metazoa_SRP (75% identical), RN7SL202P (75% identical), RN7SL716P (75% identical), Metazoa_SRP (74% identical), RN7SL850P (74% identical), RN7SL155P (72% identical), Metazoa_SRP (72% identical), RN7SL356P (71% identical), and 703 more.